MIR498 (microRNA 498)
Synonyms: hsa-mir-498; MIRN498; mir-498
Gene: MicroRNA gene on chromosome 19 (53,674,197 to 53,674,320, forward strand). Ensembl gene ENSG00000207869.
Gene Ontology:
Biological process: miRNA-mediated post-transcriptional gene silencing
Cellular component: RISC complex
Diseases named in the same sentence as MIR498 in open-access papers:
MIR498 is named in the same sentence as 2 diseases in open-access papers, as found by Europe PMC text mining. Sharing a sentence is not in itself a finding about the gene and the disease. The quoted sentences say what the papers report.
esophageal cancer (1 paper, 2016). A primary or metastatic malignant neoplasm involving the esophagus. "Follow-up experiments indicated transfection of MIR20b, MIR30e, MIR498 and MIR196 affected the apoptotic pathway in esophageal cancers cells." (PMID 27462775, 2016). "Collectively, above results suggested that the four predicted miRNAs, MIR20b, MIR30e, MIR498 and MIR196 may be involved in the apoptotic pathway in esophageal cancers cells." (PMID 27462775, 2016).
MIR498 also shares sentences with these, for which no sentence is quoted: tumours (1 paper).